SPX (spexin hormone)
Description:
Plays a role as a central modulator of cardiovascular and renal function and nociception. Also plays a role in energy metabolism and storage. Inhibits adrenocortical cell proliferation with minor stimulation on corticosteroid release (By similarity). [Spexin-1]: Acts as a ligand for galanin receptors GALR2 and GALR3. Intracerebroventricular administration of the peptide induces an increase in arterial blood pressure, a decrease in both heart rate and renal excretion and delayed natriuresis. Intraventricular administration of the peptide induces antinociceptive activity. Also induces contraction of muscarinic-like stomach smooth muscles. Intraperitoneal administration of the peptide induces a reduction in food consumption and body weight. Inhibits long chain fatty acid uptake into adipocytes (By similarity). [Spexin-2]: Intracerebroventricular administration of the peptide induces a decrease in heart rate, but no change in arterial pressure, and an increase in urine flow rate. Intraventricular administration of the peptide induces antinociceptive activity (By similarity).
Synonyms: C12orf39; MGC10946; NPQ; spexin; SPX1
Tractability: Antibody: UniProt places it where antibodies can reach, with medium confidence; UniProt predicts a signal peptide or a membrane-spanning region; its Gene Ontology location is reachable by antibodies, with medium confidence.
Gene: Protein-coding gene on chromosome 12 (21,526,296 to 21,541,249, forward strand). Ensembl gene ENSG00000134548.
Subcellular location: Secreted; Secreted, extracellular space; Cytoplasmic vesicle, secretory vesicle
Gene Ontology:
Molecular function: neuropeptide hormone activity; protein binding
Biological process: positive regulation of gastro-intestinal system smooth muscle contraction; long-chain fatty acid import into cell; negative regulation of appetite; negative regulation of heart rate; negative regulation of renal sodium excretion; positive regulation of systemic arterial blood pressure; regulation of sensory perception of pain; signal transduction
Cellular component: dense core granule; extracellular region; cytoplasm; transport vesicle
Genetic constraint (gnomAD): Loss-of-function variants: 18 observed, 15.48 expected, observed/expected ratio (o/e) 1.16, 90% interval 0.8 to 1.7. The upper end of that interval is the gene's LOEUF score, 1.7, which puts it in group 6 of 6, group 1 being the genes least tolerant of losing a copy. Missense variants: 119 observed, 110.92 expected, observed/expected ratio (o/e) 1.07, 90% interval 0.92 to 1.25. Synonymous variants: 44 observed, 44.98 expected, observed/expected ratio (o/e) 0.98, 90% interval 0.77 to 1.26.
Homologues: Orthologues: chimpanzee SPX (99% identical), pig SPX (82% identical), macaque SPX (81% identical), rabbit SPX (80% identical), guinea pig SPX (72% identical), mouse Spx (67% identical), rat Spx (66% identical), zebrafish spx (44% identical).
Diseases named in the same sentence as SPX in open-access papers:
SPX is named in the same sentence as 41 diseases in open-access papers, as found by Europe PMC text mining. Sharing a sentence is not in itself a finding about the gene and the disease. The quoted sentences say what the papers report.
Obesity (21 papers, 2012 to 2026). Accumulation of substantial excess body fat. "In human studies, a drop in serum SPX/tissue SPX expression (e.g., in omental and subcutaneous fat) has been associated with obesity, especially for adult and childhood obesity." (PMID 34276562, 2021). "In summary, SPX is a strong regulator of fat tissue metabolism, and a deficiency of this peptide leads to obesity." (PMID 34067710, 2021). "SPX is present in various brain regions and peripheral tissues, and its functional role has been associated with feeding behavior, obesity, reproduction, cardiovascular, and nociception." (PMID 31275244, 2019). "If SPX does negatively regulate the reproductive axis in mammals, then the increase in SPX expression could partially explain the underlying obesity-induced reproductive dysfunction." (PMID 35692389, 2022). "There is evidence of an increase in serum SPX levels in severely obese patients following 6 months after the Roux-En-Y gastric bypass surgery and the associated weight loss, implying dysregulation of SPX in fat metabolism during obesity." (PMID 31275244, 2019). "Therefore, the current study aimed to investigate whether SPX alleviates HFD-induced obesity by promoting white adipose browning and explore the underlying mechanism in vivo and in vitro." (PMID 38658956, 2024). "However, the underlying mechanism of SPX in treating obesity remains unclear, particularly regarding its role in promoting white adipose browning." (PMID 38658956, 2024). "Furthermore, a decreased uptake of long-chain fatty acids in adipocytes, in rodents with diet-induced obesity after peripheral SPX administration, suggests that SPX may contribute to weight loss." (PMID 36079049, 2022). "Taken together, we have for the first time demonstrated that SPX alleviated diet-induced obesity and ameliorated glucose and lipid metabolism by inducing the browning of white adipose, and the pro-browning action of SPX is mediated by JAK2/STAT3 pathway." (PMID 38658956, 2024). "Other studies confirmed that SPX levels in mouse stomachs decreased in obesity and elevated insulin resistance, closely related to PCOS." (PMID 37658762, 2023). "It was also shown that the concentration of SPX was lower in newborns with a small size compared to gestational age (SGA), in which the risk of obesity and overweight in the future is higher and correlated with length, body weight, and head circumference." (PMID 37761477, 2023). "Recent studies have highlighted SPX functions in the control of obesity and energy metabolism based on the observed relationships between SPX and obesity: the circulating level of SPX is low in obese individuals compared to their normal counterparts." (PMID 35204737, 2022). "Despite the increasing knowledge on the role of SPX in the metabolism of metabolic disorders such as diabetes or obesity, there are still some pieces required to solve this puzzle." (PMID 35052420, 2021). "Other research has also shown that the SPX concentration in serum is downregulated during obesity and diabetes." (PMID 34067710, 2021). "They showed that the SPX gene is one of the most downregulated genes in adipose tissue during obesity and that SPX administration reduced food intake in mice." (PMID 34067710, 2021). "SPX (spexin hormone) and APOB (apolipoprotein B) are a critical proteins plays an important role in obesity associated type 2 diabetes mellitus." (PMID 33902539, 2021). "Following the findings of its ability to act as a satiety factor, the functional role of SPX was further examined in obesity/ fat metabolism-related diseases, such as metabolic syndrome and diabetes mellitus." (PMID 31275244, 2019). "These functional studies, as a whole, are in line with the idea that SPX acts as an adipokine, which plays a vital role in the regulation of fat metabolism and therefore a potential target for obesity treatment." (PMID 31275244, 2019).
Obesity (continued). "SPX as hormone has been shown to be involved in weight regulation with potential for obesity therapy as well as presence of gestational diabetes." (PMID 30254709, 2018). "SPX’s regulatory roles in energy balance, as well as glucose and lipid metabolism, facilitate the development of innovative therapeutic approaches for treating chronic conditions such as obesity, diabetes, and cardiovascular diseases." (PMID 41597393, 2026). "The potential use of SPX as an anti-obesity treatment has been reported in recent studies." (PMID 38658956, 2024). "Given the emerging advancement in the domain of small peptides, SPX may serve as a promising strategy for the treatment of obesity and metabolic diseases." (PMID 38658956, 2024). "Collectively, all these studies indicated SPX may serve as a potentially useful agent to reduce obesity and improve glucose metabolism." (PMID 38658956, 2024). "Consistently, previous studies also demonstrated the anti-obesity effect of SPX." (PMID 38658956, 2024). "Thus, further studies should be performed to evaluate the relationship between SPX, obesity, and thermogenesis and the mechanisms involved in subcutaneous and visceral WAT." (PMID 38339044, 2024). "In addition, SPX is closely related to the pathogenesis of glucose and lipid metabolism-related diseases, including obesity, diabetes, and non-alcoholic fatty liver." (PMID 35883602, 2022). "Therefore, we decided to check whether obesity affects the concentration of SPX in the mother’s peripheral blood (MB) and umbilical cord blood (UCB)." (PMID 37761477, 2023). "While low SPX levels are observed in metabolic disorders such as obesity and type 2 diabetes (T2DM), exercise can raise SPX levels, improving insulin sensitivity and glucose tolerance." (PMID 41597393, 2026). "Therefore, SPX may serve as a new therapeutic candidate for treating obesity." (PMID 38658956, 2024). "Although the topic of SPX in the context of changes in its concentration in umbilical cord blood has already been discussed in the literature, we do not find data on obesity as a variable factor in these studies." (PMID 37761477, 2023). "In the future, more understanding of the physiological effects of GAL and SPX with three GALRs could lead to the development of new therapeutic strategies such as neuroendocrine-based obesity elimination and reproductive abnormalities using GAL and SPX." (PMID 35692389, 2022). "In the present study, oil-red O staining showed that SPX promoted ectopic fat distribution in intra-lobular areas but not in intra-acinar cell areas, supporting a reported finding of little evidence for fat accumulation within acinar cells in obesity." (PMID 23285260, 2012).
Anxiety (13 papers, 2018 to 2026). Intense feelings of nervousness, tension, or panic often arise in response to interpersonal stresses. "Furthermore, we hypothesized that SPX levels might be associated with eating disorder pathology, as well as perceived stress, anxiety, and depressiveness." (PMID 36079049, 2022). "As a neuropeptide, SPX is widely expressed in multiple regions of the nervous system and plays crucial roles in energy metabolism, anxiety regulation, and neurodevelopment." (PMID 41231350, 2025). "Studies have also shown an effect of stress and anxiety on SPX’s expression in different brain structures in animals." (PMID 36079049, 2022). "Animal studies on the effects of spexin in anxiety and depression indicate a connection between SPX and the CRH system, while the CRH system has an established connection to the serotonergic system." (PMID 36004833, 2022). "In addition, in mice in which anxiety was induced, SPX mRNA expression was reduced in the hippocampus, whereas CRF mRNA expression was upregulated." (PMID 36079049, 2022). "Therefore, further investigations of changes in peripheral SPX levels following interventions inducing stress or anxiety, e.g., by using stress paradigms such as the Trier social stress test, are needed." (PMID 36079049, 2022). "The hypothetical role of SPX in the mechanism of anxiety and depression is also speculated from its localization in brain regions that are involved in the neurobiology of stress." (PMID 32376994, 2020). "Interestingly, SPX in the medial habenula of mice and its ortholog dorsal habenula in zebrafish provide further evidence on the potential role of SPX in regulating depression and anxiety." (PMID 31275244, 2019). "SPX mRNA expression was downregulated in the amygdala and hypothalamus and upregulated in hippocampus, striatum and cerebellum after chronic administration of escitalopram in adult male rats, suggesting that SPX may influence food-intake control, anxiety responses and the HPG axis." (PMID 29488100, 2018). "Therefore, SPX may also be involved in the regulation of stress, anxiety, and depressiveness." (PMID 36079049, 2022). "Further, SPX and GAL are also involved in depression and anxiety, where studies in fish have shown a possible anxiolytic function of SPX." (PMID 35692389, 2022). "In addition, SPX and GAL have roles in modulating serotonin activity, indicating roles in mood disorders such as anxiety and depression." (PMID 35692389, 2022). "The results replicate the negative correlation of SPX with BMI and fat mass, but do not support the hypothesis that peripheral SPX plays a role in the regulation of stress, depressiveness, anxiety, eating behavior, or physical activity." (PMID 36079049, 2022). "SPX, acting as a cognate ligand for GALR2/3, could be involved in anxiety/depression." (PMID 31275244, 2019).
type 2 diabetes (11 papers, 2018 to 2026). "Recently, SPX has emerged as a new target for drug design/therapeutic strategy, e.g., for type 2 diabetes mellitus (T2DM) treatment, gastrointestinal disease treatment, and prediction of insulin resistance in patients with nonalcoholic fatty liver disease." (PMID 35883602, 2022). "SPX levels have been noted to be inversely correlated with fasting blood glucose in adults with type 2 diabetes, similar to the current study." (PMID 30254709, 2018). "This study aimed to investigate the effect of 8 weeks of high intensity interval training (HIIT) on insulin resistance through liver gluconeogenesis, lipolysis, inflammation, oxidative stress, and lipogenesis in Type 2 diabetic rats with a special focus on the role of SPX." (PMID 40841811, 2025). "However, taking into account SPX’s metabolic role, it is interesting to investigate its functions in insulin resistance (IR) and glucose homeostasis in type 2 diabetes mellitus (T2DM)." (PMID 31263247, 2019).
depression (9 papers, 2019 to 2026). "Recently, SPX has also been shown in the medial habenula of mice and dorsal habenula of the zebrafish, an evolutionary conserved brain area involved in the regulation of depression and anxiety." (PMID 32376994, 2020).
type 2 diabetes mellitus (9 papers, 2018 to 2026). A type of diabetes mellitus that is characterized by insulin resistance or desensitization and increased blood glucose levels. "Further studies are necessary to determine whether SPX is associated with harder outcomes such as atherosclerosis and diabetes in the general population." (PMID 30254709, 2018). "The level of SPX decreases during diabetes, and its concentration is correlated with fasting blood glucose levels." (PMID 38136826, 2023). "In both type 1 and type 2 diabetes mellitus patients, SPX levels are reduced in serum and negatively correlate with blood glucose levels." (PMID 31275244, 2019). "However, these previous results and ours support the theory that SPX plays a role in glucose homeostasis and may serve as a biomarker for impaired glucose regulation seen in diabetes." (PMID 31263247, 2019). "In both studies, the protective role of SPX as an insulin sensitizer appears only true among subjects without established diabetes." (PMID 31263247, 2019).
metabolic syndrome (8 papers, 2018 to 2026). A cluster of metabolic risk factors for CARDIOVASCULAR DISEASES and TYPE 2 DIABETES MELLITUS. "The aim of the study was to determine whether circulating levels of spexin (SPX) is associated with components of metabolic syndrome (MetS)." (PMID 30254709, 2018). "Also, circulating SPX levels are significantly lower in obese children and patients with metabolic syndrome or remain unchanged in obese adolescents." (PMID 31275244, 2019).
gestational diabetes (6 papers, 2018 to 2021). Carbohydrate intolerance first diagnosed during pregnancy. "SPX is also elevated in gestational diabetes patients, along with a positive correlation increase in glucose concentration levels while decreased in pregnant women without gestational diabetes." (PMID 31275244, 2019).
Insulin resistance (6 papers, 2018 to 2025). Increased resistance towards insulin, that is, diminished effectiveness of insulin in reducing blood glucose levels. "These improvements coincided with elevated hepatic SPX signaling and are associated with reduced insulin resistance." (PMID 40841811, 2025). "Spexin (SPX) is a novel neuropeptide and adipokine negatively correlated with obesity and insulin resistance." (PMID 37658762, 2023). "Recently, in addition to the proposed functional role of SPX in lipid metabolism, glucose homeostasis and insulin resistance, serum level of SPX was found to be decreased with age in healthy women investigated." (PMID 31275244, 2019). "In summary, these studies have establish the potential role of SPX as a biomarker of metabolic parameter, in particular insulin resistance." (PMID 31275244, 2019). "Therefore, further targeted studies are warranted to clarify whether SPX acts via GALR2 to influence insulin resistance and hepatic metabolism, and to explore the involvement of the FOXO1/PGC-1α pathway in these processes." (PMID 40841811, 2025). "Low levels of SPX may aggravate insulin resistance, thereby promoting liver fat accumulation." (PMID 40172394, 2025).
polycystic ovarian syndrome (4 papers, 2021 to 2025). "We observed decreased spexin (SPX) levels in granulosa cells (GC) and follicular fluid collected from obese and polycystic ovarian syndrome women, and we noted an inhibitory effect of SPX on GC proliferation and steroidogenesis." (PMID 37658762, 2023). "Interestingly, recent studies suggest that SPX may be a novel key player in the pathophysiology of polycystic ovarian syndrome (PCOS); the serum level of SPX is inversely associated with androgens and metabolic profiles in PCOS women." (PMID 37658762, 2023). "In women with the reproductive disorder, polycystic ovarian syndrome (PCOS), circulating SPX levels are low compared to women with normal menstrual cycles." (PMID 35692389, 2022).
anorexia nervosa (3 papers, 2021). A disorder most often seen in adolescent females characterized by a refusal to maintain a minimally normal body weight, an intense fear of gaining weight, a disturbance in body image, and, in postmenarcheal females, the development of amenorrhea. "Spexin (SPX), a highly conserved neuropeptide, is known to have diverse functions and has been implicated/associated with pathological conditions, including obesity, diabetes, anorexia nervosa, and anxiety/mood disorders." (PMID 34276561, 2021).
mood disorder (3 papers, 2019 to 2022). A cognitive disorder a disturbance in which the person's mood is hypothesized to be the main underlying feature. "As such, GAL and SPX are involved in similar processes, namely, in energy regulation, reproduction, stress responses and mood disorders." (PMID 35692389, 2022). "Thus, steering SPX action through GAL2 receptor is an optimal approach to simultaneously resolve both mood disorders and abnormal appetite/body weight." (PMID 31057364, 2019). "Together, SPX and GAL2 receptor are likely connected to the key regulatory system controlling or linking appetite and mood behaviors, allowing optimal treatment for comorbid mood disorders and abnormal body weight." (PMID 31057364, 2019).
Hypertension (2 papers, 2025 to 2026). The presence of chronic increased pressure in the systemic arterial system. "In contrast, hypertension shows that genes like SLC16A7, SPX, and PAX8 are less central, indicating they play a reduced role in the vascular and kidney networks." (PMID 40909129, 2025).
iron deficiency (2 papers, 2018 to 2024). "Emerging findings on the involvement of SPX genes in other important processes (i.e. disease resistance, iron deficiency response, low oxygen response and phytochrome-mediated light signalling) were also highlighted." (PMID 29298909, 2018).